MIR6793 (microRNA 6793)
Synonyms: hsa-mir-6793
Gene: MicroRNA gene on chromosome 19 (10,828,973 to 10,829,035, forward strand). Ensembl gene ENSG00000275640.
Homologues: Orthologues: chimpanzee MIR6793 (100% identical).